CRP (C-reactive protein)
Diseases named in the same sentence as CRP in open-access papers (continued):
Sharing a sentence is not in itself a finding about the gene and the disease.
infection (continued). "It is also possible that the severity of infection was lower in WRA, as evidenced by generally lower CRP and AGP concentrations, which could explain the weak and inconsistent effect of inflammation on PZC in WRA." (PMID 32266402, 2020). "Several reports found that the use of IL-6 or CRP were not suitable for diagnosing infection after shoulder arthroplasty, with the sensitivity of both tests less than 50%." (PMID 33008442, 2020). "For protection, however, CRP must be injected into mice within a few hours of administering pneumococci, that is, CRP is protective against early-stage infection but not against late-stage infection." (PMID 33117400, 2020). "Both CRP and SAA can respond immediately after infection or tissue damage." (PMID 32713370, 2020). "As an acute phase reactant, CRP is not a specific infection marker in isolation and can be elevated in various inflammatory and infective conditions." (PMID 32843693, 2020). "On the other hand, CRP and IL-6 combination displayed excellent specificity and would allow to rule out infection reliably." (PMID 32927683, 2020). "Common clinical presentations included extremely high fever and chest/back pain with high levels of CRP without any signs of infection." (PMID 33122662, 2020). "As for CRP, it is hard to interpret early PJI because studies have shown that CRP will elevate as long as 3 months after the surgery even in the absence of infection." (PMID 32316949, 2020). "The biochemical workup revealed no abnormal indications of infection (including C-reactive protein (CRP) levels, erythrocyte sedimentation rate (ESR) and T-SPOT)." (PMID 32948151, 2020). "C-reactive protein (CRP) is a stable, nonspecific, and sensitive serum marker of systematic inflammation secreted by hepatocytes in response to infection." (PMID 32309764, 2020). "Nonetheless, serum levels of CRP, a strong indicator for systemic inflammation or infection, were not markedly elevated in all three groups and were not significantly different between the groups." (PMID 31949271, 2020). "This seems to be its universal shortcoming, given that low PPVs are commonly reported for CRP in surveillance of infections also following non-transplant operations." (PMID 32127631, 2020). "Serum levels of C-reactive protein (CRP) have been used for several decades as a marker of the acute phase reaction that can be induced both by acute and chronic states as a systemic reaction to inflammation, injury, or infections." (PMID 32707721, 2020). "The patient considered as no infection had been treated with a one-stage knee revision procedure; his pre-operative serum CRP and ESR were both negative, as well as the synovial white blood cell count (1.350 cells/uL) and the leukocyte esterase." (PMID 32585959, 2020). "Inflammatory markers such as CRP and ESR may be beneficial but cannot definitively diagnose the condition or exclude infection." (PMID 32421502, 2020). "In 65 German adult blood donors without recurrent infection or elevated C-reactive protein levels, two had IgG2 levels >2 SD below the mean." (PMID 33048985, 2020). "CRP is the most commonly researched acute-phase reactant in infection and noninfectious inflammation." (PMID 32722722, 2020). "With respect to laboratory tests, erythrocyte sedimentation rate and C-reactive protein values are usually higher during bone infections; however, these are non-specific tests that are not related to infection severity." (PMID 32380709, 2020). "Second, some biomarkers of infection or inflammatory, such as CRP, as well as PCT, was not measured and analyzed." (PMID 31964345, 2020). "Further, we used a single measure of CRP to indicate chronic inflammation while repeated measures are understood to be better to rule out increased levels due to infection." (PMID 33141863, 2020).
infection (continued). "Still, serum levels of C-reactive protein (CRP) > 5 mg/L occur in ~25% of the patients in the absence of any identifiable infection, consistent with some kind of proinflammatory state." (PMID 32318071, 2020). "CRP was slightly higher in the adenovirus and enterovirus/rhinovirus infection groups than in the negative group (p=0.29 and 0.32, respectively)." (PMID 32256905, 2020). "Patients with cancer or infections present commonly increased CRP values, but not decrease albumin value." (PMID 32344777, 2020). "The negative predictive value of CRP < 7.0 and no infection was 100% in cases of AF (91.0–100, 95% CI) and 100% in cases of chronic pain (80.5–100, 95% CI)." (PMID 32053936, 2020). "CRP had the highest AUC to identify AC from individuals without AC or other infections (AUC 1.000, sensitivity 100.0%, specificity 100.0%, positive predictive value 100.0%, and negative predictive value 100.0%)." (PMID 32508526, 2020). "CRP is a nonspecific acute-phase protein induced by IL-6 and a sensitive biomarker of inflammation and infection." (PMID 33031060, 2020). "Overall, the data indicate that E-CRP-1, unlike WT CRP, is protective against infection regardless of the time point of injecting E-CRP-1." (PMID 33117400, 2020). "CRP is a sensitive and nonspecific inflammatory marker in acute phase of inflammation and infection." (PMID 32220241, 2020). "The patients in this study did not have infection or inflammation and, thus, did not undergo measurement of the CRP level." (PMID 30718566, 2019). "Some studies reported CRP and PCT levels were higher in infection than flare in SLE patients." (PMID 30994732, 2019). "It was found that pigMAP was not elicited after infection with PRRSV, while Hp and CRP were used successfully to assess disease caused by PRRSV." (PMID 31001544, 2019). "Biomarkers such as procalcitonin (PCT) and C-reactive protein (CRP) are already well established in the field of infectiology, whilst elevated lactate levels can reflect significant infection-related cellular dysfunction despite being increased due to other pathophysiological abnormalities." (PMID 30736862, 2019). "Unconfirmed infections were defined as culture negative infections that neither fulfilled the criteria for clinical infection (clinical symptoms, maximum CRP >30 mg/L, and treatment for at least 5 days)." (PMID 31709209, 2019). "However, given the low prevalence of depleted iron stores (SF <15 μg/L) and the correction of SF values for inflammation and infection by measuring both AGP and CRP, our assessment of iron status based on SF alone can still be considered accurate." (PMID 31754277, 2019). "Firstly, the correlation of PCT, CRP and N% with organ failure and infection in patients with SAP is not explored." (PMID 31993385, 2019). "C-reactive protein (CRP) and procalcitonin (PCT) are widely used biomarkers of infections." (PMID 31821331, 2019). "In conclusion, while native CRP is protective only against early stage infection, non-native CRP is protective against both early stage and late stage infections." (PMID 30863393, 2019). "In the current study, in the plasma we did not noted any differences of systemically infection-related inflammatory mediators (such as a leukocyte, hs-CRP, neutrophile granulocyte, ESR and uric acid) between CSVD patients and healthy subjects." (PMID 31440388, 2019). "CRP, as an acute-phase protein, is a non-specific protein reacting to acute inflammation, infection, and tissue damage." (PMID 30847301, 2019). "The high percentage of subjects with elevated plasma levels of CRP, in the absence of infection, is in agreement with the anticipation that the Western lifestyle is associated with low-grade chronic inflammation." (PMID 31195706, 2019). "C-reactive protein (CRP) is a member of the pentraxin family and is an acute-phase response to plasma protein; its level in blood increases rapidly in response to trauma, inflammation, and infection." (PMID 31667269, 2019).
infection (continued). "CRP is therefore commonly used as a non-specific laboratory indicator for infection, systemic inflammation, and tissue damage." (PMID 31428091, 2019). "Notably, reduced C-reactive protein levels were observed with both ZS2058 and LGG, which suggests abrogated anti-infection and inflammatory responses." (PMID 30842764, 2019). "So, its production is restricted to infection rather than the degree of inflammation, unlike CRP whichincreases in cases of SIRS even without bacterial infection." (PMID 30717340, 2019). "After 18 days of treatment in our ward, the infection apparently resolved, with negative control BCs, and normal C-reactive protein (CRP) and PCT levels." (PMID 30665450, 2019). "In comparison with non-infectious SLE patients (387.9±261.6/μL), CD4+T cells count decreased significantly in infectious SLE patients (217.8±150.4/μL) (P<0.05), and it was negatively correlated with infection-related indicators including PCT (r=−0.573, P=0.041) and CRP (r=−0.596, P=0.032) levels." (PMID 30994732, 2019). "C-reactive protein (CRP) has been reported to be an acute-phase response to plasma protein; its level in blood increases rapidly in response to trauma, inflammation, and infection." (PMID 31667269, 2019). "CRP also protects mice from the early stages of infection with Salmonella enterica serovar Typhimurium, which is a gram negative bacterium and to which CRP does not bind in vitro." (PMID 30863393, 2019). "CRP and PCT are the biomarkers most widely used in screening of infection in septic patients." (PMID 30623257, 2019). "CRP was not protective when mice received CRP 24 h after infection, suggesting that CRP is protective during early stage infection but not in late stage infection." (PMID 30863393, 2019). "CRP levels ≤ 20 mg/L indicate a self-limited LRTI for which antibiotics are not needed, and CRP ≥ 100 mg/L indicate severe infection for which antibiotics should be prescribed." (PMID 30987144, 2019). "Many studies have focused on the role of inflammatory markers such as erythrocyte sedimentation rate (ESR) and C - reactive protein (CRP), as well as pro-calcitonin (PCT) to predict the onset of inflammation and infection, especially in bacterial involvement of diabetic wounds." (PMID 31555767, 2019). "Although serum CRP and ESR are the most commonly used serological markers in PJI diagnosis, they did not perform well in some situations such as low-virulence organism infection and indolent microorganism infection." (PMID 31783874, 2019). "Finally, they found that elevated CRP and NLR levels can be used as a predictor of active infection in SLE patients with a high specificity." (PMID 31163082, 2019). "The distribution of the polymorphisms of CRP, TNF, and IL10 genes showed no significant changes irrespective of a previous infection or not with Chlamydia." (PMID 30804931, 2019). "We detected PCT, CRP and LDH in children’s serum specimens, investigated their correlation with infection and tumour progression and further provided evidence for identification of paediatric malignant solid tumour concurrent with infection and tumour progression." (PMID 30976022, 2019). "On the contrary, although plasma C-reactive protein (CRP) is elevated in almost all patients with PUUV infection, a high CRP level does not indicate a more severe disease." (PMID 31438470, 2019). "Another limitation is that the PCT had not been compared with the other infection markers such as CRP, interleukin or leucocyte count." (PMID 31496894, 2019). "The aim of this study was to explore antibiotic use among neonates with and without confirmed infection, with emphasis on choice and dosing of antibiotics, treatment duration, CRP values and the use of BSA." (PMID 31709209, 2019). "Our data also showed that both CRP and PCT levels were higher in SLE patients with infection." (PMID 30994732, 2019). "One big advantage of IL-6 over CRP and PCT is an immediate response to infection." (PMID 31022834, 2019).
infection (continued). "The homology with CRP, that was first discovered in the serum of patients with acute pneumococcal pneumonia and is upregulated in the context of inflammation and infections, prompted investigations on the involvement of PTX3 as biomarker of infections." (PMID 31031772, 2019). "Large studies on the response of C-reactive protein to antibiotic therapy in infections are lacking." (PMID 31528337, 2019). "When patients were stratified based on the severity of H1N1 infection, those with severe disease outcome had about 1.6-fold higher average levels of CRP compared to their counterparts with the non-severe infection (90 ± 44 vs. 55 ± 31 mg/L, p < 0.005)." (PMID 30288556, 2019). "As per the follow up ESR & CRP values, clinically and radiologically no patients had any evidence of infection." (PMID 35240761, 2019). "According to their study, PCT is not a better marker of infection than CRP, among critically ill patients." (PMID 31691767, 2019). "All cases of infection showed an increase in CRP levels compared to non-infected controls, but CRP levels could not distinguish between the infection types, showing that it is infection in general that causes CRP levels to increase, rather than the type of infection." (PMID 29706967, 2018). "CRP values increase with the severity of the infection but do not provide further information on short or long-term outcome." (PMID 30234089, 2018). "Although only a small proportion of cases was diagnosed on the bases of minor criteria, it should be mentioned that the values of purulence or of the CRP as indicators for infection persistence have not been ultimately determined and remain controversial." (PMID 30009171, 2018). "This is consistent with a retrospective study on the variability in response to IVIG, which showed a higher rate of concomitant infection and higher CRP levels in complete non-responders to IVIG treatment compared to partial non-responders and responders." (PMID 30332473, 2018). "Infection is suspected when fever (≥37.3 °C) persists for no less than three days and C-reactive protein increases after remission of AAV." (PMID 29902982, 2018). "If serum CRP level is very high (>20 mg/L) without any apparent explanation such as infection or chronic inflammatory illness, we will inform the GP and the participant will be excluded from the study." (PMID 30244217, 2018). "This agrees with studies showing CRP can induce NO production in both the presence and absence of infection." (PMID 30013561, 2018). "In particular, CRP, an acute phase protein that is a non-specific marker of inflammation, is one of the most commonly used biomarkers during infection management in clinical practice." (PMID 29211877, 2018). "WBC count was higher in the infection group (median 10,400/mm3 vs. median 7000/mm3, p < 0.001); however, CRP level was not different between the two groups." (PMID 29415715, 2018). "Interestingly, even in this analysis, levels of IFNγ, TNFα, IP-10, sCD163 and CRP in Group 4 became comparable to those of Group 5, which initiated ART one week post-infection (p = ns)." (PMID 30161247, 2018). "However, he did not have the typical symptoms of calcific myonecrosis at the time of his visit to the hospital; instead, there was evidence of infection, including a sensation of warmth, redness, and elevated ESR and CRP." (PMID 30235769, 2018). "C-reactive protein (CRP) is a well-described acute phase reactant that is synthesized by the liver in response to pro-inflammatory cytokines 4 to 6 h after an initial trigger, like infection or tissue injury." (PMID 29382319, 2018). "In the original ERNIE2 trial, we have shown that POC CRP without guidance did not reduce antibiotic prescribing in children with acute non-severe infections in primary care in comparison to usual care." (PMID 30354904, 2018).
infection (continued). "Activation of the classical pathway is by antibody (including non-specific immunoglobulin M (IgM) produced during infection), or by C-reactive protein (CRP), an acute phase protein." (PMID 29351189, 2018). "This was also noted by Healy and Freedman who showed that CRP levels can be used only as a method of detecting infection, rather than distinguishing it." (PMID 29706967, 2018). "Further, a large proportion of SIRS patients presented with an infection, but without evidence of bacteraemia putatively contributing to the low predictive capacity of CRP." (PMID 30111827, 2018). "One explantation of an endoprosthesis and two exchanges of a spacer were performed without an infection (pre-operative clinical signs of infection – elevated CRP; but post-operatively no signs of infection in histology and bacterial culture)." (PMID 29892047, 2018). "C-reactive protein was however higher in cases with concurrent infections compared to cases without concurrent infection (148±96 versus 112±65 mg/L, p = 0.03)." (PMID 30332473, 2018). "Inflammatory proteins (ESR, CRP) are non-specific markers related to infection, injury and neoplasia." (PMID 29490633, 2018). "Standard biomarkers for infection, such as a white cell count (WCC), erythrocyte sedimentation rate (ESR) and C-reactive protein (CRP), may be elevated in both conditions." (PMID 30225546, 2018). "Laboratory results were negative for infection, with normal CRP (0.27 (<1.0 mg/dL)), ESR (21 (0–30 mm/h)), and WBC (9.4 (4.5–11K/μL))." (PMID 29607251, 2018). "C-reactive protein (CRP) and erythrocyte sedimentation rate (ESR) values were significantly higher before prosthesis removal and reconstruction or spacer exchange (p = 0.00; p = 0.013 and p = 0.039; p = 0.002) in the infection persistence group." (PMID 29321073, 2018). "Following exclusion of patients with an infection before or on day of ICU admission, the AUC of suPAR on day 0 for predicting an infection later was 0.62 (95% CI 0.43–0.80) compared to 0.50 (0.29–0.71) for CRP." (PMID 30071826, 2018). "Findings that favor the diagnosis of SLE fever over infection include leukopenia (not explained by cytotoxic therapy), normal or slightly elevated CRP, low C3 and C4, and elevated anti-dsDNA." (PMID 29581911, 2018). "Evidence suggests that CRP is an important regulator of inflammatory processes and not just a marker of inflammation or infection." (PMID 29706967, 2018). "We performed systemic survey such as whole body CT and blood test including CRP to check and rule out endogenous infection." (PMID 29070018, 2017). "Nevertheless, if in a patient with elevated CRP an infection can be ruled out a high suspicion for recurrence will remain that will prompt the clinical and radiological examinations to diagnose or rule out tumor recurrence." (PMID 28514756, 2017). "When patients were stratified by infection status, we observed increases in TNF-α, CRP, TGF-β, IL-4, IL-6, IL-10, IL-17, and IL-23, and a decrease in IFN-γ in both uninfected and infected patients when compared with control subjects at most of the three time points." (PMID 27682880, 2017). "Unlike PCT, CRP was not useful in diagnosing the presence of infection, irrespective of the presence or primary graft dysfunction." (PMID 28704503, 2017). "One of the patients had after the 2nd doses of BI-505 a sustained period of low-grade fever (19 days) and moderate, spontaneously resolving, C-reactive protein increase (15 days), without evidence of infection." (PMID 28158311, 2017). "While CRP test does serve as a general marker for infection and inflammation, it is not specific enough to diagnose a particular disease." (PMID 28241813, 2017). "All subjects presented ultra-sensitive CRP concentrations below 10 mg/dL, indicating absence of infection." (PMID 27598983, 2017). "Previous data have shown that CRP is a sensitive and non-specific inflammatory marker of human infection or traumas." (PMID 28977869, 2017).